E2F1 (E2F transcription factor 1)
Diseases named in the same sentence as E2F1 in open-access papers (continued):
Sharing a sentence is not in itself a finding about the gene and the disease.
tumor (continued). "The results showed that the tumor of mice treated with NCi grew larger and faster than those of mice treated with 205i and E2F1, respectively." (PMID 34292880, 2021). "The IKKα–E2F1–Bmi1 cascade activated by B cells controls prostate regeneration and tumor recurrence and regulates the renewal function of tumor stem cells." (PMID 34977871, 2021). "Additional functional genes involved in tumor progression regulated by E2F1 need to be further identified." (PMID 34350181, 2021). "miR-1258 played an inhibitory role in the progression of GBM and functioned as a tumor suppressor by down-regulating E2F1 expression and attenuated E2F1-mediated downstream gene PCNA and MMP2 transcriptions." (PMID 34079762, 2021). "Based on microarray, some common markers of proliferation (such as E2F1 and MCM2-MCM6) were detected by comparing normal and tumor samples, and these genes were commonly associated with the expression of a core set of cell cycle-associated genes." (PMID 34650921, 2021). "Downregulation of HNF4α in HCC results in upregulation of lnc‐APUE, leading to enhanced E2F1 expression and in turn accelerating G1/S transition and tumor growth." (PMID 33854885, 2021). "For the “Pathway in cancer” pathway, a total of 18 risk lncRNAs synergistically regulated ER (ESR1), E2F (E2F1 and E2F2), CyclinA1 (CCND1), and Survivin (BIRC5), which indirectly leads to tumor cell proliferation." (PMID 34149805, 2021). "It was found that the mRNA and protein expression of E2F1 was higher in tumor tissues than in normal tissues." (PMID 34758200, 2021). "Recent studies also indicate that E2F1 is significantly upregulated in late-stage tumors and contributes to tumor invasion and migration." (PMID 33986804, 2021). "The protein E2F1 is a member of the E2F family of transcription factors and plays a crucial role in the control of cell cycle and action of tumor suppressor proteins." (PMID 33801990, 2021). "In this study, we found that the cholesterol esterification inhibitor avasimibe can suppress tumour proliferation and metastasis in vitro and in vivo accompanied by upregulation of E2F-1 protein expression." (PMID 34461908, 2021). "Similar results were reproduced in vivo where miR‐107 overexpression or E2F1 inhibition blocked tumor growth in nude mice." (PMID 34758200, 2021). "Previous studies suggest that the interaction between miRNA-205 and E2F1 plays an essential role in anti-tumor chemotherapy resistance." (PMID 34292880, 2021). "The MIR4435-2HG- and ELFN1-AS1-associated ceRNA subnetworks affected and regulated the expression of the COL5A2, LOX, OSBPL3, PLAU, VCAN, SRM, and E2F1 target genes and were found to be related to prognosis and tumor-infiltrating immune cell types." (PMID 33750326, 2021). "Aberrant activation of E2F1 promotes tumor progression through cell cycle-stimulating effect-mediated unrestrained cell proliferation, leading to the unfavorable prognosis of cancer patients." (PMID 33986804, 2021). "E2F1 can promote the proliferation of tumor cells and reduce the sensitivity of tumor cells to radiotherapy and chemotherapy." (PMID 34499617, 2021). "Our study confirmed that E2F1 mRNA levels were correlated with tumor grade and were increased in high grade lesions." (PMID 33430425, 2021). "For example, various mouse models unequivocally showed that E2f1 and E2f3 can both act as tumor suppressors or oncogenes, depending on tissue context." (PMID 33922435, 2021). "As a controversial transcription factor, E2F1 not only promotes the proliferation of tumor cells but also induces senescence and apoptosis." (PMID 34499617, 2021). "Playing a dual role in tumorigenesis, E2F1 is closely related to tumor progression and chemo-resistance." (PMID 33726845, 2021). "In laryngeal squamous cell carcinoma, miR-1205 is down-regulated, which regulates tumor progression through interaction with E2F1." (PMID 34180753, 2021).
tumor (continued). "Some studies have revealed that E2F-1 depletion can promote the expression of low-density lipoprotein receptors and thus influence the development of tumours by affecting lipid uptake by tumour cells." (PMID 34461908, 2021). "The transcription levels of E2F1/3/5/8 are obviously up-regulated in PAAD and the high expression of E2F2/3/6/8 was apparently associated with the tumor stage of patients with PAAD." (PMID 33604289, 2020). "E2F1 activity is normally restrained by feedback mechanisms, however when oncogenes are activated and/or tumor suppressors are inactivated E2F1-mediated transcription is unrestricted and DNA replication stress ensues." (PMID 33665206, 2020). "E2F8 overexpression in HCC facilitated the tumor occurrence and aggressiveness through activating a E2F1/Cyclin D1 signaling pathway to regulate the G1-S transition or transcriptionally suppressing CDK1 to induce hepatocyte polyploidization." (PMID 31990034, 2020). "Studies have found that oncolytic adenovirus can exert anti-tumor effects through autophagic cell death induced by the E2F1-MIR-7 epidermal growth factor receptor (EGFR) pathway." (PMID 32069901, 2020). "Other groups and we have identified HELLS as a transcriptional downstream target gene of E2F1 that is overexpressed in cancer and contributes to tumor progression." (PMID 32071286, 2020). "Lastly, the review introduces some reflections on how E2F1 activity is integrated with checkpoint control through post-translational regulation, and proposes an exploitable tumor weakness based on this axis." (PMID 33665206, 2020). "ICOVIR-7 is a modified ICOVIR-5 that includes four palindromic E2F-1 sites in the promoter instead of one, increasing E1A expression in tumor cells." (PMID 33066689, 2020). "As a tumor suppressor gene or oncogene, E2F1 is closely related to tumor progression and drug resistance." (PMID 33008330, 2020). "Most of these genes (STAT5B, CDK6, CDK2, CDKN1B, E2F8, and E2F1) showed high mRNA expression in tumor tissues compared to adjacent non-tumor tissues." (PMID 32807134, 2020). "Altered tumor suppressor and oncogenic signaling pathways often result in direct or indirect interference with E2F1 regulation to ensure higher rates of cell proliferation independently of external cues." (PMID 33665206, 2020). "EZH2 cooperates with E2F1 to enhance its transcriptional activity and control the mRNA expression of genes involved in the regulation of tumor aggressiveness via direct protein binding." (PMID 33614480, 2020). "Targeting tumor cells with a defective Rb-pathway, the E2F-1 promoter has been employed for control of E1A to facilitate tumor-selective replication." (PMID 33202717, 2020). "We previously also reported that FGF9 bound and activated FGFR2 to promote the ERK1/2 and Rb/E2F1 pathways, and subsequently increased the expression of cyclins and CDKs to enhance cell proliferation and tumor growth both in vitro and in vivo." (PMID 33172093, 2020). "A nude mouse xenograft model of cisplatin treatment showed that the tumor volume was increased in the Si-E2F1 group compared with that in the group with cisplatin treatment alone." (PMID 31897226, 2020). "E2F1 is a dual role regulator in cancer progression, where increases in E2F1 can either lead to apoptosis or promote tumor growth and invasion in cancers." (PMID 32354165, 2020).
tumor (continued). "MYC acts as a transcriptional factor that regulates the transcription of over 15% of human genes, such as CCND, CDK4 and E2F1, which are involved in tumour progression." (PMID 31907353, 2020). "E2F1 was more expressed in invasive than in non-invasive tumours in the whole series (p = 0.004) and in STs (p = 0.01)." (PMID 32316225, 2020). "Most significantly, a coincidence was apparent between the expression of PRMT5 and E2F1 in human tumours, and elevated levels of PRMT5 and E2F1 correlated with poor prognosis disease." (PMID 32709847, 2020). "In this virus, Δ24-E1A is transcriptionally controlled by a promoter harboring E2F-1 responsive elements to boost replication in tumor cells through a positive feedback loop." (PMID 33202717, 2020). "In human tumor cells, overexpressed E2F1 is involved in multidrug resistance; E2F1 increases the activity of the MDR1 promoter, resulted in higher P-gp levels." (PMID 31897226, 2020). "E2F1 is highly expressed in a variety of tumor tissues and cells, and it plays a role as a cancer-promoting gene." (PMID 33070516, 2020). "This review discusses how dysfunctional tumor suppressor and oncogenic signaling pathways promote the disruption of E2F1 transcription and hence of its transcriptional targets, and how such events have the potential to drive DNA replication stress." (PMID 33665206, 2020). "The functions of E2F1 on normal or early tumor versus advanced cancer stages are dynamic and context-specific." (PMID 32863950, 2020). "As a transcriptional factor, E2F1 participated in the tumor growth and metastasis in many types of human cancers, including HCC." (PMID 33614480, 2020). "The self-suppression of EBNA1 mRNA translation causing E2F1 induction helps to explain two previous independent animal models showing an inverse correlation between EBNA1 protein expression levels and tumour phenotype." (PMID 32453417, 2020). "H19 closely correlates with the degree of tumor differentiation and promotes PC cell proliferation by modulating the expression of E2F-1, a direct target of H19-derived miR-675-5p 7,16." (PMID 32626524, 2020). "It has been reported that oncogenes, such as ras and E2F1, can induce DSBs in tumor cells, leading to the genomic instability which characterizes the vast majority of human cancers." (PMID 31358914, 2020). "Of these genes, E2F1 is an important transcriptional mediator in cancer progression and has both oncogenic and tumor-suppressive properties." (PMID 32354165, 2020). "Inactivation of RB1 expression in tumor cells leads to the deregulation of activity of transcription factors E2F1, E2F2, and E2F3, which control the expression of genes involved in differentiation, development, proliferation, and apoptosis." (PMID 32429447, 2020). "Further, PRMT5 and E2F1 regulate invasion and migration, and in human tumours we identified a coincidental expression between PRMT5, E2F1 and motility-related genes." (PMID 32709847, 2020). "TIMER analysis revealed that the E2F1 expression is remarkably positively related to tumor purity (r = 0.347, P = 2.46e − 13) in GBM." (PMID 33381564, 2020). "This suggests that E2F1 is targeted by certain miRNAs and is involved in the regulation of tumor cells." (PMID 33008330, 2020). "It has been shown that E2F1 induces genes involved in DNA repair in normal cells and in tumor cells undergoing chemotherapy through complex formation on the promoters of these genes." (PMID 32655498, 2020).
tumor (continued). "We found, using tumour cells where the E2F1 gene had been genetically inactivated combined with chemical ablation of PRMT5 enzyme activity, that E2F1 is important for PRMT5 to maintain cancer cell viability." (PMID 32709847, 2020). "In the whole series, invasive tumours showed higher E2F1 gene expression than non-invasive ones (p = 0.004)." (PMID 32316225, 2020). "In fact, the E2F1 levels were found upregulated in the corticotroph tumor cells, whereas they were abrogated by EGFR inhibition." (PMID 31487906, 2019). "In this study, we identified that decreased expression of TFAM impaired the proliferation of tumour cells by inducing G1/S phase arrest and reducing the expression of E2F1, phospo‐Rb, PCNA and TK1." (PMID 31062473, 2019). "The reactive oxygen species (ROS)-induced DNA damage response promotes tumor immunity by binding the transcription factor E2F1 to the E2F1 binding site adjacent to the transcription initiation site of the MICA promoter." (PMID 30813924, 2019). "Immunohistochemistry analysis showed an organized tumor tissue and highly expressed E2F1 in PBS and SG400-EGFP injected mice." (PMID 31278126, 2019). "It induces cell apoptosis by blocking anti-apoptotic pathways, while inhibiting tumor cell multiplication and malignant transformation through p27-cyclin-E-pRb-E2F1- cell cycle control and HIF-1alphaVEGF antiangiogenic pathways." (PMID 30741976, 2019). "In summary, our results indicated that the mRNA expression levels of E2F1, E2F3, E2F5, and E2F8 were significantly upregulated, and obvious and negatively associated with tumor stage for OC." (PMID 30967995, 2019). "Among the 15 identified, expressions of genes such as TUBG130, TERT31, and MYBL232 have already been shown to be E2F1-dependent in various tumor settings." (PMID 31601969, 2019). "With shRNA and E2F1 knockdown strategies, it was demonstrated that the reduction of E2F1 expression inhibits tumour formation, pointing to E2F1 as a key player in BL lymphomagenesis." (PMID 31683676, 2019). "miR-106b is reported to promote the tumor growth through targeting tumor suppressor genes, such as Pten, Cdkn1a, E2F1, Setd2, Runx3, Smad7, Cdkn1a, and Bim." (PMID 31547867, 2019). "The human E2F-1 promoter was operably linked to E1A in SG400-E2F1 and SG400-E2F/IL-15 to restrict expression of E1A to Rb pathway-defective tumor cells." (PMID 31278126, 2019). "E2F1 is a gene positively correlated with protein expression levels and is up-regulated in all tumor types studied." (PMID 30809433, 2019). "E2 promoter binding Factor 1 (E2F1) is a transcriptional activator mainly known to regulate the cell cycle, apoptosis and angiogenesis to support tumor progression." (PMID 31921839, 2019). "The transcription factor E2F1 is involved in the cell cycle and in proliferation, apoptosis, and differentiation and can act as a tumor suppressor or oncogene." (PMID 32010624, 2019). "E2F1, the most classic member of the E2F family, was found to play roles in both proliferation and apoptosis and exhibited a complex role in tumor development regulation." (PMID 30967995, 2019). "Further analyses of the tumor samples with immunohistochemical (IHC) suggested that E2F1 staining intensity decreased when miR-338-3p and miR-362-3p binding sites were both mutated, in comparison with wild-type SBF2-AS1." (PMID 31071530, 2019). "Mechanistically, MZF1 regulates the expression of proline synthetic genes, while MZF1‐AS1 interacts with PARP1 to enhance its interaction with E2F1, resulting in upregulation of MZF1 and other oncogenic genes associated with tumor progression." (PMID 31592410, 2019). "HULC not only increases the expression of E2F1, but also sequesters miR-107, which is an inhibitor of E2F1, to promote tumor angiogenesis." (PMID 31480503, 2019).
tumor (continued). "Transcription factor E2F1 is a major target for RB to exhibit its tumor suppression efficacy, un- or hypo-phosphorylated RB binds to E2F1, leading to the inhibited expression of E2F1 target genes and arrested G1/S cell cycle transition." (PMID 31258527, 2019). "All these data indicate that ANP32E induces cell cycle progression by upregulating E2F1, which subsequently promotes tumor proliferation in TNBC." (PMID 29633513, 2018). "It is suggested that the E2F transcription factor 1 (E2F1) is both an oncogenic inducer and a tumor suppressor." (PMID 29596435, 2018). "E2F1 (network 1, out-degree 147) can stimulate apoptosis and function as a tumor suppressor, while the TCF3 fusion (network 4, out-degree 207) has been found in adenocarcinomas in situ." (PMID 29303984, 2018). "Treating these lymphomas with CAL-101 suppressed the expression of Myc and E2F1 and killed the tumor cells." (PMID 30486342, 2018). "In conclusion, our studies strongly support the finding that, at least in DDLS and MLS, the HMGA1/E2F1 and NFkB pathways are involved in the mechanism of tumor progression and trabectedin resistance." (PMID 29980789, 2018). "Research has revealed that E2F1’s overexpression in GC prompted an outspread of cell death through various mechanisms, therefore proving the role of E2F1 in tumour suppression in GC." (PMID 30487158, 2018). "These patients’ higher expression of E2F1 was shown to have a poor survival, due to increased tumour sizes and higher tumour stages." (PMID 30487158, 2018). "It participates in tumor drug resistance through both antagonizing E2F1-induced apoptosis and, the induction of autophagy in tumor cells." (PMID 30235236, 2018). "Pax8 also promoted tumor cell growth by increasing transcription of the cell cycle regulator E2f1 through direct binding to the E2f1 promoter in a complex with the RB protein." (PMID 30096791, 2018). "Deregulated E2F7 activity in cancer would thus be expected to impact on tumour cell growth both through its ability to modulate E2F1 activity as well as by influencing protein production through altered Pol I activity." (PMID 29760477, 2018). "A role for ASXL1 as a tumor suppressor was suggested by the altered gene expression by Asxl1 deletion and the upregulation of genes involved in cell-cycle progression (e.g., E2F1 target genes such as Nmyc)." (PMID 30389914, 2018). "The treatment of cells with CAL-101 prevents GAr-mediated induction of E2F1 and, interestingly, it also suppresses E2F1 levels in non-EBNA1 expressing tumor cell lines." (PMID 30486342, 2018). "By contrary, the expression of E2F1 gene in the same panel increases in all tumours, three of them with fold-changes higher than 1.5." (PMID 29661169, 2018). "The top scoring network in this analysis was centered on E2F1, further supporting a role of oncomotif-miRNAs in regulation of tumor cell proliferation." (PMID 27477696, 2017). "Recent reports showed that E2F1 took part in tumour invasion and metastasis by regulating thrombospondin 1, PDGFR and VEGFR." (PMID 29115924, 2017). "There have been previous reports demonstrating that E2F1 mediates tumor metastatic dissemination by up-regulating fibronectin." (PMID 28264467, 2017). "In summary, this is the first report to demonstrate that ANKRD22 exhibits oncogene activity that promotes tumor progression in NSCLC through the transcriptional regulation of E2F1." (PMID 28667340, 2017). "Recently, several papers have reported that E2F1 can induce EMT in different tumour cells, but the mechanisms described in these studies are inconsistent." (PMID 29115924, 2017). "In fact, the role of E2F1 in cancer modulation is controversial and it acts as both a tumor promoter and suppressor." (PMID 29312618, 2017).